NRAS (NRAS proto-oncogene, GTPase)
Diseases named in the same sentence as NRAS in open-access papers (continued):
Sharing a sentence is not in itself a finding about the gene and the disease.
thyroid cancer (continued). "Genetic and epigenetic alteration of the RAS–RAF–MEK–MAPK–ERK pathway, and mutations in NRAS, KRAS, and BRAF, have been shown to strongly influence the development of thyroid cancers." (PMID 33915745, 2021). "Of the 50 thyroid nodule cases, BRAF, NRAS, and TERT promoter mutation correctly detected thyroid cancer respectively in 12, 7, and 5 cases from 39 malignancy cases." (PMID 33247684, 2020). "Molecular genetic analyses revealed several frequent DNA anomalies in thyroid cancer, including the mutations of BRAF, NRAS and RET/PTC genes, the prognostic significance of which is still debated in the individual subcategories of thyroid carcinoma." (PMID 30666518, 2019). "RAS mutations (KRAS, NRAS, and HRAS) are found at a relative low frequency in differentiated thyroid cancers compared with the more common BRAF mutations." (PMID 27127178, 2016). "As gain-of-function mutations in NRAS are found in a minority of FVPTCs, overexpression of IGF2BP2 would be an intriguing alternative that leads to enhanced NRAS signalling in thyroid cancer with follicular histology." (PMID 25923053, 2015). "Taking these facts into consideration, the results of this study allow us to conclude that low expression of MLH1 is associated with BRAF V600E mutations and RET/PTC rearrangements and transitions (IDH1 and NRAS) in patients with thyroid carcinoma." (PMID 23414134, 2013). "Therefore, our results raise the question about the clinical utility of BRAF, KRAS, NRAS, and TERT promoter mutation analysis using ctDNAs of patients with thyroid cancers." (PMID 33915745, 2021). "Additional biomarkers including NRAS and TERT promoter mutations are acknowledged to have a potential clinical significance in thyroid cancer and could be applied in synergy with BRAF mutation." (PMID 33247684, 2020). "Taken together, the additional molecular testing of BRAF, NRAS, and TERT promoter mutations not only enabled the identification of thyroid malignancies in FNAB cytology but also allowed the prediction of the aggressive characteristics of thyroid cancer." (PMID 33247684, 2020). "However, in terms of diagnostic utility, BRAF, NRAS, and TERT promoter mutations have shown greater potential due to the high prevalence and clinical features in thyroid cancer." (PMID 33247684, 2020). "Multiple molecular abnormalities have been described in thyroid cancers arising from ovarian teratomas, including point mutations in BRAF (V600E and K601E) 67% of cases and KRAS and NRAS as well as loss of heterozigocity in the PTEN region and ret/PTC rearrangements." (PMID 27882257, 2016). "In differentiated thyroid cancers such as PTC and FTC, a limited number of mutations such as BRAF p.V600E, RET translocations (CCDC6::RET, NCOA4::RET, etc.), H/K/NRAS mutations such as NRAS p.Q61R, and PAX8::PPARG translocation are often found, and these are mutually exclusive." (PMID 38672067, 2024). "In PDX models of colorectal and thyroid cancers, we observed significant inhibitory effect of the combination of selumetinib and KRT-232 on tumor growth across a spectrum of MAPK genomic backgrounds, including BRAF, KRAS, and NRAS mutations, compared to single-agent treatment with either drug." (PMID 35075200, 2022). "Except for BRAF, HRAS, NRAS and TG, whose involvement in PTC is deeply revealed, for the other commonly mutated genes in all tumor stages, we further assayed the relationship between TCGA data, the RNA expression level of thyroid cancer-derived cell lines and their mutational status." (PMID 35996174, 2022).
thyroid cancer (continued). "Although the low number of NRAS mutations generally deteced in this collective did not allow to draw far conclusions, based on these limited data a direct carcinogenetic effect in HT-related thyroid cancer, mostly of papillary type, seems to be unlikely." (PMID 30666518, 2019). "This approach identified significant dependencies on key genes/proteins such as KRAS, NRAS, PABPC1, PPP2R1A, STAG2, and BRAF in thyroid cancer cell lines, underscoring their potential as critical therapeutic targets." (PMID 40297138, 2025). "The therapeutic potential of the DNA ligase IV inhibitor should need further validation on thyroid cancer cell lines characterized by different cancer genetic drivers (e.g. BRAF p.V600, NRAS p.Q61K)." (PMID 38380364, 2024). "For instance, only two known cancer genes were found to be mutated in over 5% of thymomas (MUC16 and HRAS), testicular germ cell tumours (KRAS and KIT), and thyroid carcinomas (BRAF and NRAS)." (PMID 37550388, 2023). "Many somatic genetic alterations, including those in BRAF, HRAS, KRAS, NRAS, PTEN, and HER1, have had fundamental roles in the tumorigenesis of thyroid carcinoma." (PMID 31655978, 2020). "Thyroid cancer has these types of SNV-drivers present in BRAF in 55.8% of cases, the next qualifying genes being TTN, TTN-AS1, NRAS and KMT2C all with a low incidence rate of 1.3%." (PMID 31530827, 2019). "In thyroid carcinoma (THCA), 5.23% were BRAF p.V600E, 0.65% were NRAS p.Q61R, and 0.25% HRAS p.Q61R." (PMID 30890735, 2019). "Many somatic genetic alterations including those in BRAF, HRAS, KRAS, NRAS, PTEN, and HER1 have been revealed to play fundamental roles in the tumorigenesis of thyroid carcinoma." (PMID 27833153, 2016). "Given that NRAS is the second most common oncogenic driver in PDTCs and ATCs, developing this model is a crucial step for advancing our understanding of RAS-driven thyroid cancers." (PMID 39874138, 2025). "Gene mutations were found in the NRAS, KRAS, BRAF, and KIT genes and were similar to those in thyroid carcinoma, but some patients (37.5%) did not exhibit any gene mutations." (PMID 33763376, 2021). "The limitation of the current study may be that we failed to prove the clinical utility of BRAF, KRAS, NRAS, and TERT promoter mutation as circulating markers in early-staged thyroid cancers distinguishing from benign thyroid lesions or healthy individuals." (PMID 33915745, 2021). "The targeted next generation sequencing of thyroid nodules revealed BRAFV600E as the most prevalent mutation in patients with thyroid cancer (45% of examined nodules) and either no mutation or mutation in the RAS gene (NRAS Q61R, HRAS Q61K) in benign thyroid lesions." (PMID 31620364, 2019).
breast cancer (78 papers, 2004 to 2025). A primary or metastatic malignant neoplasm involving the breast. "We have previously uncovered a gene signature associated with NRAS expression in basal-like breast cancer." (PMID 36258226, 2022). "The higher accuracy exhibited by the RFCB method in the prediction of the NRAS protein level in breast cancer cell lines, supports its usage in disease status evaluation, as overexpression of NRAS is associated with poor prognosis in breast cancer." (PMID 28420336, 2017). "We have shown previously that this cell line has high levels of NRAS (as compared to cell lines of other breast cancer subtypes) and NRAS can promote tumor growth of these cells in vivo." (PMID 36258226, 2022). "Instead, we have shown previously that wild-type NRAS is selectively overexpressed in the basal-like breast cancers." (PMID 36258226, 2022). "Previous works showed high expression of HRAS, KRAS, and NRAS in breast cancer compared with benign breast tissue; deletions of HRAS but no other mutations in RAS family members; and rare amplifications." (PMID 36358725, 2022). "We have previously shown that NRAS is highly expressed selectively in basal-like subtypes of invasive breast cancers and can promote their growth and progression." (PMID 36258226, 2022). "We found that CHD7 expression was positively correlated with a small subset of classical oncogenes, notably NRAS, in breast cancer." (PMID 28649742, 2017). "In contrast, entities such as breast cancer or HNC display a predominance of PIK3CA mutations (around 40%, for an overall mutation rate of KRAS, NRAS and HRAS inferior to 5% in both cases)." (PMID 28532501, 2017). "Knockdown of CHD7 inhibits cell proliferation and decreases gene expression of several CHD7 targets, including NRAS, in breast cancer cell lines." (PMID 28649742, 2017). "Instead, NRAS is a well-known oncogene, often constitutively active in breast cancer, along with PI3K members and regulators, which are also miR-223 predicted targets." (PMID 24400121, 2014). "For the first time, we have identified somatic mutations in genes related to the AKT/MAPK signaling pathways, such as EGFR, PIK3CA, KRAS, HRAS and NRAS, in brain metastases of breast cancer and other types of cancer." (PMID 20604919, 2010). "Interestingly, 38 and 44% decreases in the levels of the farnesylated and acylated NRAS were observed in the two breast cancer cell lines, MDA-MB-231, and MDA-MB-468, respectively, while HRAS levels showed a 36% decrease only in MDA-MB-468 cells." (PMID 36961909, 2023). "Invasive breast cancers showed higher NRAS mRNA levels compared to DCIS samples." (PMID 36258226, 2022). "Our data indicate that these miRNAs may be involved in FOXO1 and NRAS modulation, breast cancer development, and progression." (PMID 34299605, 2021). "Previous mechanistic research has shown that miR-145 could regulate cell proliferation by targeting TGF-β1 in breast cancer, by targeting NRAS in condyloma acuminatum, and by regulating ADAM19 in retinoblastoma." (PMID 32614357, 2020). "NRAS Q61K missense mutation in the ectodermal group mainly occurs in the patients with skin cancer, while splice acceptor GATA3 X309_splice mutations only present in the breast cancer cases derived from ectoderm." (PMID 33308219, 2020). "Also, wild-type NRAS, upregulated in basal-like breast cancer, promotes tumorigenesis through IL-8 secretion via JAK2 activation." (PMID 31781501, 2019). "The active mutants of HRAS, KRAS, and NRAS were found in a subset of breast cancers." (PMID 30111373, 2018). "Interestingly, miR-340 overexpression was also able to decrease NRAS protein levels in three different breast cancer cell lines (BT-549, MDA-MB-231, MCF7) and two NSCLC cell lines (A549, Calu-1)." (PMID 26799668, 2016).
breast cancer (continued). "When BRAF V600E and non-synonymous changes in KRAS or NRAS were considered, methylation of the 5′UTR of C7orf49 and of the probe cg00172872 in the intergenic region on 12q21.33 remained significantly associated with trametinib in pancancer and breast cancer (5.24 × 10–13 ≤ pFDR ≤ 0.0023)." (PMID 33676569, 2021). "In breast cancer MDA-MB-468 cells, HRAS and NRAS were depleted, and in MDA-MB-231 cells, only NRAS was depleted." (PMID 38540084, 2024). "KRAS, NRAS and HRAS, referred to as oncogenic RAS, gained our attention from the viral carcinogenesis pathway, breast cancer pathway and renal cell carcinoma pathway." (PMID 35422066, 2022). "Here increased CSTF3 expression triggers APA shortening of both NRAS proto-oncogene, GTPase (NRAS) and Jun proto-oncogene, AP-1 transcription factor subunit (JUN), oncogenes previously shown to be deregulated in breast cancer." (PMID 32560344, 2020). "For MCF-7 breast cancer cells, data showed a significant decrease in the mRNA levels of BCL-2, KRAS and NRAS oncogenes and some of the YWHA family." (PMID 29444163, 2018). "In this study, we revealed that CHD7 likely regulates a small set of oncogenes, such as NRAS and MYCN, in breast cancer." (PMID 28649742, 2017). "When adjusted for standard of care (ESCAT I‐II) genes (i.e., PIK3CA, ESR1, and ERBB2 for breast cancer; KRAS, NRAS, and BRAF for colon cancer, etc.), 37 (3.6%), 0 (0%), 1 (0.2%), and 0 (0%) of mutant alleles would have been negative among breast, bowel, lung, and skin cancer samples, respectively." (PMID 40056420, 2025). "For wild type NRAS it has been shown that its overexpression enhances invasiveness of basal-like breast cancer cells, but a driver role of wild type NRAS has not been demonstrated." (PMID 38987766, 2024). "By gene silencing, NRAS has been demonstrated to be necessary for the growth of basal-like breast cancer cells but not that of luminal breast cancer cells or the closely related claudin-low cells." (PMID 36258226, 2022). "Interestingly, NRAS and HRAS result to be overexpressed in basal-like and HER2 tumors, the most aggressive subtypes of breast cancer." (PMID 31781501, 2019). "According to what found in other tumor types, KRAS confirms to be the most frequently mutated RAS isoform in breast cancer and its mutation, unlike mutations of HRAS and NRAS, is strongly associated with the poor clinical outcome." (PMID 31781501, 2019). "In addition, miR-133a targeting of EGFR, miR-200c and miR-30c targeting of KRAS, miR-148b targeting of NRAS, miR-7 targeting of RAF1, miR-206 targeting of RASA1 and miR-21 targeting of SPRED1 have been reported in breast cancer cells." (PMID 27462780, 2016). "For example, NRAS, a well‐characterized oncogene, was downregulated upon silencing PKD2 and silencing both PKD2 and PKD3, but not suppressed when silencing PKD3 in both MDA‐MB‐231 and MDA‐MB‐468 cells, which suggested differentially regulatory roles of PKD2 and PKD3 in breast cancer." (PMID 30652415, 2019).
acute myeloid leukemia (76 papers, 2007 to 2026). Acute myeloid leukemia (AML) is a group of neoplasms arising from precursor cells committed to the myeloid cell-line differentiation. "NRAS mutations occur in 3.03% of all cancers, predominantly in skin (10%–25%), acute myeloid leukemia (9.76%), and colon (∼4%)." (PMID 39635441, 2024). "NRAS is mutated in cutaneous melanoma and acute myeloid leukemia (AML) at 20% and 15% frequencies respectively." (PMID 37083947, 2023). "The authors compared six acute myeloid leukemia (AML) cell lines with mutations in either KRAS or NRAS against six KRAS wild type cell lines." (PMID 35740503, 2022). "Patients with acute myeloid leukemia and NRAS mutations have a low overall complete remission rate of approximately 10%." (PMID 35707364, 2022). "Mouse models of high risk (HR)-MDS and acute myelogenous leukemia (AML) post-MDS using mutant NRAS and overexpression of human BCL-2, known to be poor prognostic indicators of the human diseases, were created." (PMID 34638998, 2021). "Constitutive activation of the MAPK pathway results from gain-of-function mutations in genes encoding pathway constituents, particularly NRAS, a common finding in up to 11% of patients with acute myeloid leukemia (AML)." (PMID 33255818, 2020). "This 70-year-old man had acute myeloid leukemia with NRAS mutations (G12D, Q61R, E62K), and had received 1 prior line of therapy." (PMID 29765547, 2018). "We aimed to determine the frequency of NRAS (NRASmutant) mutation; and its prognostic significance in Egyptian children with acute myelogenous leukemia (AML)." (PMID 22220252, 2011). "In addition, NRAS mutations accompany the progression of preleukemic conditions to acute myeloid leukemia with poor prognosis." (PMID 39941834, 2025). "It is consistently demonstrated in both CMML cohorts that NRAS mutations are associated with shorter overall survival, acute myeloid leukemia-free survival, increased white blood cell count, decreased platelet values and the presence of blast cells in peripheral blood." (PMID 40372530, 2025). "Background/Objectives: NRAS mutations are found in approximately 10% of patients with acute myeloid leukemia (AML), with nearly half of those occurring at codon 12, but little is known about how differing G12 mutants affect cancer cell activity." (PMID 39941834, 2025). "In a study of 2502 patients with acute myeloid leukemia (AML), 112 were found to have NRAS mutations in codon 12, and of those 7 had a G12D mutation and 4 had a G12V mutation." (PMID 39941834, 2025). "Research has reported the occurrence of NRAS mutations in adult patients with acute myeloid leukemia (AML)." (PMID 39766793, 2024). "NRAS/KRAS mutations have been found in 20–25% of patients with acute myeloid leukemia (AML), 25–30% of patients with juvenile myelomonocytic leukemia (JMML), and 15% of pediatric patients with B- or T-lineage acute lymphoblastic leukemia (ALL)." (PMID 35422065, 2022). "Previously, we reported that dual inhibition of activated cdc42-associated kinase 1 (ACK1) and germinal center kinase (GCK) can be a novel therapeutic strategy to overcome acute myeloid leukemia (AML) harboring NRAS mutation." (PMID 34956887, 2021). "Mutations in the RAS gene family (NRAS, KRAS) are critical drivers of late-stage acute myeloid leukemia (AML) progression." (PMID 42087923, 2026). "In acute myeloid leukemia (AML), mutations in the RAS gene family, particularly in NRAS and KRAS, are clinically significant." (PMID 39857784, 2025). "NRAS gene mutations are common in various tumor diseases, such as multiple myeloma, subcutaneous melanoma, colorectal cancer, and adult acute myeloid leukemia (AML), and play an important role in the occurrence and development of these tumors." (PMID 39766793, 2024). "Indeed, Ack1 is an important therapeutic target for acute myeloid leukemia (AML) with constitutively active NRAS mutations and in chronic myelomonocytic leukemia since these mutations are sensitive to inhibitors of Ack1." (PMID 36980241, 2023).